AUTS2 (activator of transcription and developmental regulator AUTS2)
Description:
Component of a Polycomb group (PcG) multiprotein PRC1-like complex, a complex class required to maintain the transcriptionally repressive state of many genes, including Hox genes, throughout development. PcG PRC1 complex acts via chromatin remodeling and modification of histones; it mediates monoubiquitination of histone H2A 'Lys-119', rendering chromatin heritably changed in its expressibility. The PRC1-like complex that contains PCGF5, RNF2, CSNK2B, RYBP and AUTS2 has decreased histone H2A ubiquitination activity, due to the phosphorylation of RNF2 by CSNK2B. As a consequence, the complex mediates transcriptional activation. In the cytoplasm, plays a role in axon and dendrite elongation and in neuronal migration during embryonic brain development. Promotes reorganization of the actin cytoskeleton, lamellipodia formation and neurite elongation via its interaction with RAC guanine nucleotide exchange factors, which then leads to the activation of RAC1 (By similarity).
Synonyms: KIAA0442; FBRSL2; MRD26
Tractability: PROTAC: its protein half-life has been measured.
Gene: Protein-coding gene on chromosome 7 (69,598,296 to 70,793,506, forward strand). Ensembl gene ENSG00000158321.
Subcellular location: Nucleus; Cytoplasm, cytoskeleton; Cell projection, growth cone
Subcellular location (Human Protein Atlas): Nucleoplasm; Cell Junctions; Cytosol; Plasma membrane
Pathways (Reactome):
Gene expression (Transcription): RUNX1 interacts with co-factors whose precise effect on RUNX1 targets is not known
Gene Ontology:
Molecular function: chromatin binding; protein binding
Biological process: positive regulation of transcription by RNA polymerase II; actin cytoskeleton organization; axon extension; dendrite extension; heterochromatin formation; neuron migration; positive regulation of DNA-templated transcription; positive regulation of lamellipodium assembly; positive regulation of Rac protein signal transduction
Cellular component: nucleoplasm; nucleus; actin cytoskeleton; chromatin; growth cone; PRC1 complex; cytoskeleton
Genetic constraint (gnomAD): Loss-of-function variants: 16 observed, 104.8 expected, observed/expected ratio (o/e) 0.15, 90% interval 0.1 to 0.23. The upper end of that interval is the gene's LOEUF score, 0.23, which puts it in group 1 of 6, group 1 being the genes least tolerant of losing a copy. Missense variants: 1,447 observed, 1,656 expected, observed/expected ratio (o/e) 0.87, 90% interval 0.84 to 0.91. Synonymous variants: 727 observed, 681.32 expected, observed/expected ratio (o/e) 1.07, 90% interval 1 to 1.13.
Gene-disease validity (ClinGen):
ClinGen rates the evidence that AUTS2 causes each of these diseases.
syndromic intellectual disability (autosomal dominant): Definitive. A intellectual disability that is part of a larger syndrome.
Homologues: Orthologues: chimpanzee AUTS2 (99% identical), macaque AUTS2 (97% identical), dog AUTS2 (96% identical), pig AUTS2 (94% identical), mouse Auts2 (93% identical), rat Auts2 (93% identical), guinea pig Auts2 (75% identical), tropical clawed frog auts2 (74% identical), zebrafish auts2a (62% identical), rabbit AUTS2 (60% identical). Paralogues in human: FBRSL1 (32% identical), FBRS (29% identical).
Diseases named in the same sentence as AUTS2 in open-access papers:
AUTS2 is named in the same sentence as 83 diseases in open-access papers, as found by Europe PMC text mining. Sharing a sentence is not in itself a finding about the gene and the disease. The quoted sentences say what the papers report.
autism (73 papers, 2010 to 2025). Persistent deficits in social interaction and communication and interaction as well as a markedly restricted repertoire of activity and interest as well as repetitive patterns of behavior. "The AUTS2 gene is named for autism susceptibility, but it affects nerve development and muscle function, and pathogenic variants can lead to symptoms such as intellectual disability, microcephaly, reduced muscle tone or limb spasms." (PMID 40893940, 2025). "In males, association was also observed with a variant in the autism risk gene intellectual developmental disorder, autosomal dominant 26 (AUTS2) (rs17684339, p = 9.59 × 10–8)." (PMID 40708016, 2025). "The autism susceptibility candidate 2 (AUTS2) was identified as a risk gene for ASD in human genetic studies." (PMID 38200558, 2024). "The three genes affected by PAE in both brain and the liver tissues were the Autism Susceptibility Gene 2 (Auts2), Androglobin (Adgb), and RNA Binding Protein Fox 1 (Rbfox1) genes." (PMID 39239947, 2024). "For example, there is a higher incidence of alcoholism in the family members of ASD patients compared with the general population; also, there is a link between the autism susceptibility candidate 2 gene (AUTS2) in the regulation of alcohol consumption." (PMID 39902246, 2024). "Our previous study found that the deletion of high-risk gene Autism Susceptibility 2 (AUTS2) in mice led to dentate gyrus (DG) hypoplasia that highly associated with impaired social novelty recognition." (PMID 37215664, 2023). "Auts2 encodes a PRC1-associated transcriptional activator essential for normal neuronal gene expression, and haploinsufficiency of Auts2 is associated with ID and autism." (PMID 35731217, 2022). "MG was also associated with SNPs in the brain- and neuron-specific genes, including cerebellum 4 precursor (CBLN4), potassium channel KCNH5, adenylate cyclase 8 (ADCY8), and autism susceptibility candidate gene AUTS2." (PMID 35711735, 2022). "AUTS2, i.e. autism-susceptibility-gene-2, encodes an activator of transcription and regulates neurodevelopment." (PMID 36329495, 2022). "The AUTS2 gene plays major roles during brain development and is associated with various neuropathologies including autism." (PMID 36078102, 2022). "Although the AUTS2 gene was named for autism susceptibility, many AUTS2 syndrome patients have an outgoing personality in childhood." (PMID 35431798, 2022). "Autism susceptibility candidate 2 (AUTS2) is one among recently identified autism susceptibility candidate genes, whose function in neuronal circuits is unclear." (PMID 34544758, 2021). "The autism susceptibility candidate 2 (AUTS2) gene is one such gene, associated with ASDs, intellectual disability and a range of other neurodevelopmental conditions." (PMID 34544758, 2021). "Autism susceptibility candidate 2 (AUTS2) has emerged as a crucial gene associated with a wide range of neuropsychological disorders, such as ASD, ID, schizophrenia, and epilepsy." (PMID 35011572, 2021). "Oksenberg N., Stevison L., Wall J.D., Ahituv N. Function and regulationof AUTS2, a gene implicated in autism and human evolution." (PMID 33659799, 2020). "Autism susceptibility candidate 2 (AUTS2) gene has been associated with various psychiatric disorders, such as autism and intellectual disabilities." (PMID 32498016, 2020). "Although predominantly associated with neurological disorders (e.g., autism), dysregulation of AUTS2 has been implicated in both lung adenocarcinoma and prostate cancer." (PMID 33143142, 2020). "Autism susceptibility candidate 2 (AUTS2), a risk gene for autism spectrum disorders (ASDs), is implicated in telencephalon development." (PMID 33305180, 2020).
autism (continued). "This region contains the AUTS2 gene, and the deletion of the AUTS2 gene has been reported to be associated with autism, intellectual disability, short stature, and microcephaly." (PMID 33584783, 2020). "As knowledge was gathered, the view of AUTS2 gene changed from an “autism susceptibility candidate gene” to a cause of a syndromic form of ASD (“AUTS2 syndrome”), with frequently associated ID, microcephaly and craniofacial abnormalities." (PMID 31134136, 2019). "No QTL was identified for LMW, and the SNP Chr20_2198171 C > G, located near the autism susceptibility candidate 2 gene (AUTS2), was the only potentially significant QTL for LMWP." (PMID 30606130, 2019). "Rare variant analysis on a cohort level confirmed the association of five genes with autism (AUTS2, NHS, NSD1, SLC9A9, and VPS13)." (PMID 31134136, 2019). "Significantly greater than expected number of rare variants were detected in 5 of the 101 tested autism-linked genes: AUTS2, NHS, NSD1, SLC9A9, and VPS13B." (PMID 31134136, 2019). "In Patient 2 (P2) a rare mutation was detected in autism susceptibility candidate 2 (AUTS2), which previously was associated with syndromic ASD form." (PMID 29458409, 2018). "These two regions are located in the intron region of two distinct genes, anaplastic lymphoma receptor tyrosine kinase (ALK), and autism susceptibility candidate 2 (AUTS2)." (PMID 28203233, 2017). "The autism susceptibility candidate 2 (AUTS2) gene is associated with various neurological disorders, including autism and brain malformation." (PMID 28626003, 2017). "Nevertheless, previous studies show that genomic rearrangements involving AUTS2 are associated with autism and intellectual disability." (PMID 27734896, 2016). "The autism susceptibility candidate 2 (AUTS2) was initially suspected to be associated with ASD found in a pair of monozygotic twins which had a de novo balanced translocation which disrupted the AUTS2 locus." (PMID 26483618, 2015). "Many studies have shown that AUTS2 is associated with autism, alcohol consumption, heroin dependence and suicide." (PMID 25347278, 2014). "The autism susceptibility candidate 2 (AUTS2) gene has been reported to be associated with autism, suicide, alcohol consumption, and heroin dependence." (PMID 25347278, 2014). "AUTS2 was first associated with autism by studies of monozygotic twin pairs with an identical balanced translocation." (PMID 23437340, 2013). "The newly identified interacting genes include AUTS2, mutations of which are associated with autism and intellectual disabilities." (PMID 24265791, 2013). "In the dyslexia cohort, two unrelated families carried CNVs on chromosome 7q11.23 that involved the autism susceptibility candidate 2 (AUTS2, MIM# 607270)." (PMID 22102821, 2011). "AUTS2, encoding a subunit of the Polycomb Repressive Complex 1-like complex, is associated with neural development and identified as a candidate risk gene for autism." (PMID 40446031, 2025). "Genes reported as potential blood biomarkers of mental health, such as PACSIN1 and SPTBN1 (associated with addiction-related behavior), GPR19 (associated with depression), and AUTS2 (associated with autism), were highlighted in the STRING analysis of this study." (PMID 40917096, 2025). "Human-specific boundaries were also associated with several genes implicated in brain disease and development, such as the Autism Susceptibility Candidate 2 (AUTS2) gene, a key regulator of transcriptional networks and a mediator of epigenetic regulation in neurodevelopment." (PMID 38062027, 2023). "Also, the links between the autism susceptibility candidate 2 gene (AUTS2), a known ASD risk gene, in the regulation of alcohol consumption was reported." (PMID 28935972, 2017). "At one side of the deletion is the gene AUTS2 (Autism susceptibility candidate 2, 7q11.22)." (PMID 27734896, 2016).
autism (continued). "The Tbr1 null animal was chosen because Tbr1 is a developmentally related transcription factor that binds, among other targets, the promoter of a gene called autism susceptibility candidate 2 (Auts2), named for its implication in autism susceptibility in the frontal cortex." (PMID 24245670, 2013). "AUTS2 (Autism susceptibility candidate 2) is a nuclear protein that is highly expressed in developing neurons of certain brain regions, notably the frontal cortex and cerebellum, and has been linked with the neuropathy of autism." (PMID 22347364, 2012). "Autism susceptibility candidate 2 (Auts2) is a gene associated with autism and mental retardation whose exact function is unknown, but is expressed in different regions of the mouse brain." (PMID 22347364, 2012). "Also, the imprinted gene Dio3 in male pups, while H19 and Xist in female pups, were upregulated by high gestational folic acid supplementation, accompanied by different expressional changes in the candidate autism susceptible gene Auts2 between male and female pups." (PMID 36386900, 2022). "Notably, autism susceptibility candidate 2 (Auts2) contained five hypomethylated intronic DMLs in F1 cortex; exonic mutations in this gene cause a syndromic form of intellectual disability through its involvement in neuronal migration, neuritogenesis, and transcriptional regulation." (PMID 33407853, 2021). "In addition to abnormalities in growth, craniofacial structure, learning and memory, and behavior, 16Gso homozygotes display distinct pathologies of the cerebellum and hippocampus that are similar to those associated with autism and other types of AUTS2-linked neurological disease." (PMID 31554716, 2019). "AUTS2 is a highly conserved protein, primarily expressed in the brain in various neuronal cell types including glutamatergic, GABAergic, and dopaminergic neurons, as well as in regions implicated in autism neuropathology, such as the cerebral cortex and cerebellum." (PMID 28626003, 2017). "(S) Log-normalized counts of transcripts for the autism-related transcription factor Auts2 and several neurotransmitter receptor and ion channel genes whose expression changes across postnatal development (Glra1, Grin2b, Kcnj3, and Kcnq3)." (PMID 36876911, 2023). "Deletion of a human-specific boundary near the autism-related AUTS2 gene results in the upregulation of this gene in neurons." (PMID 38062027, 2023). "Imbalanced expression of Auts2 affects neurodevelopment and neurological function, which results in autism-like and other neurological disorders in zebrafish." (PMID 36672612, 2022). "Another well-known gene in autism is AUTS2, and this study reported upregulation of AUTS2 expression in ASD LCLs compared with control LCLs." (PMID 35743705, 2022). "One of the autism candidate genes, AUTS2 is involved in neuritogenesis via Rac1 signaling activation in the developing brain." (PMID 34260616, 2021). "Transcriptomic analysis revealed a down-regulation of autism-related (Shank3, Auts2, Ctnnd2, Nrxn2) and glutamatergic (Grm4) genes in aggressivemice." (PMID 33659799, 2020). "Rare mutations in other autism related genes such as CNTNAP2 and CHD8 are also associated with both autism and macrocephaly,while mutations in the risk genes AUTS2 and DHCR7 give rise to autism and microcephaly." (PMID 26076356, 2015). "While current research has started to address the function of AUTS2 in neuronal growth and development, much work needs to be done to determine the molecular mechanism by which AUTS2 leads to the pathogenesis of autism." (PMID 26483618, 2015). "The AUTS2 gene was first identified as a candidate gene for autism when it was shown to be disrupted by a translocation breakpoint in a pair of autistic twins." (PMID 24690944, 2014).
autism (continued). "The Carboxi-terminal part of Drosophila Tay presents homology with mammalian AUTS2, a neuronal nuclear protein that is related to autism, mental retardation, Attention Deficit Hyperactivity Disorder, and alcohol drinking behaviour." (PMID 24348264, 2013). "A balanced translocation involving the autism susceptibility candidate 2 (AUTS2; GenBank NM_001127231.1) gene in a pair of monozygotic twins with ASD was the first to link this gene to autism." (PMID 23349641, 2013). "Subsequently, balanced and/or unbalanced chromosomal rearrangements including AUTS2 were found in other cases of autism as well as mental retardation, epilepsy, dyslexia and attention deficit hyperactivity disorder (ADHD)." (PMID 23437340, 2013). "Previous studies of de novo chromosomal translocations and inversions identified breakpoints within AUTS2 in individuals with autism and/or ID phenotypes." (PMID 22102821, 2011). "Mutations of AUTS2 (and also in gene CADPS2) are implicated in autism." (PMID 34073168, 2021). "The deletion of patient PS6 overlaps the AUTS2 gene, a susceptibility candidate gene for autism that is not related to PS-involved tissues." (PMID 27884122, 2016). "In our snRNA-seq dataset, of all tested diseases, genes associated with autism (DOID:12849) were overrepresented (Fisher’s exact test, OR = 10.2, Padj = 8.52 × 10−16) among the top 100 Purkinje cell marker genes, including RORA [fold change (FC) = 331.9], AUTS2 (FC = 43.1), and SHANK2 (FC = 13.8)." (PMID 37824616, 2023). "Regulation of expression of both AUTS2 and IMMP2L by wig-1 suggests a possible role for wig-1 in autism." (PMID 22347364, 2012). "Notably, 22 out of the 45 reported (candidate) genes are known to be related to a broader phenotype than DLD, including intellectual disability, epilepsy, and/or autism (e.g., GRIN2A, CNTNAP2, CNTNAP5, AUTS2)." (PMID 38298611, 2024). "It is worth noting though that some individuals with disrupted AUTS2 and mental retardation or autism have additional, potentially non-neuronal phenotypes, such as hypotonia, short stature, urogenital abnormalities, and skeletal abnormalities." (PMID 23349641, 2013). "Our data indicate that expressions of BDNF, Grm3, Foxp1, Auts2 and Shanks3 in the hippocampus are significantly induced by L-serine administration in GHRH-KO mice via changed expression of epigenetic markers, which may ameliorate impairment of memory and autism-related behavior." (PMID 36672612, 2022).